MCM2 (minichromosome maintenance complex component 2)
Diseases named in the same sentence as MCM2 in open-access papers (continued):
Sharing a sentence is not in itself a finding about the gene and the disease.
breast cancer (continued). "MCM2 was overexpressed in CSCs from glioblastoma (GBM), colon cancer, and breast cancer." (PMID 36303105, 2022). "A recent study indicated that high expression levels of CCNE2 would increase the combination with minichromosome maintenance protein MCM2 and MCM7 of the pre-replication complex, subsequently promoting genomic instability and cell proliferation in breast cancer." (PMID 36233194, 2022). "MCM2 is a sensitive biomarker for cancer cell proliferation in keeping with classical markers proliferating cell nuclear antigen (PCNA) and Ki-67, and performs even better in colorectal cancer, breast cancer, and esophageal squamous cell carcinoma (ESCC)." (PMID 36303105, 2022). "These suggest that Hph-1-gp70 targeting MCM2 may be effective in TNBC cells and CSC-like breast cancer cells." (PMID 36303105, 2022). "The protein expression results of TUBB3, MCM2, MYOC, FN1, S100A7, and TFF1 were consistent with the mRNA expression result COL10A1, LEP, PLIN1, PGM5-AS1, and TRHDE-AD1 were capable of discriminating luminal A breast cancer and normal controls." (PMID 35692369, 2022). "And the dysfunction of MCM2 was found to be correlated with the progression and poor prognoses of many cancer types, such as lung cancer, HCC, cervical cancer, breast cancer, oral squamous cell carcinoma, prostate cancer and pancreatic cancer." (PMID 36303105, 2022). "In our analysis, we identified that MCM2 and MCM4 are vital to the survival of breast cancer." (PMID 33816496, 2021). "In our current study, we evaluated nuclear protein markers either expressed throughout (Ki67, MCM2), from post G1 (Cyclin A) or in M-phase (PHH3) of the cell cycle and their connections with the routinely used predictive and prognostic factors in breast cancer." (PMID 31446607, 2020). "We aimed to analyze the expression of cell-cycle regulation markers – minichromosome maintenance protein 2 (MCM2), Ki-67, Cyclin-A and phosphohistone-H3 (PHH3) − in pre-treatment core-biopsy samples of breast carcinomas in correlation with known predictive and prognostic factors." (PMID 31446607, 2020). "More importantly, we also found that the prognostic significance of Cdc6 expression in the breast cancer patient cohort was independent of the prognostic significance of MCM2-7 genes." (PMID 28428557, 2017). "Genes enriched in the top breast cancer cell lines are TOP2A, HER3, CDC25B, MCM2 and TUBB." (PMID 28754978, 2017). "Here, we show that MCM2 is highly expressed in clinical samples of invasive carcinoma of the breast, especially triple-negative breast cancer (TNBC), and in cancer stem cell (CSC) marker-positive breast cancer cells." (PMID 26430873, 2015). "The identified DEGs, which were involved in cell cycle, including CDC20, BUB1, GLIPR1, MCM2, and CCNB1, could have a crucial function in the development of breast cancer, and may become potential targets or prognostic markers for breast cancer." (PMID 25385471, 2015). "MCM2 and MCM3 seem to have the most important role in several types of neoplasia, including alimentary system tumors, genitourinary system tumors, lung cancer, breast cancer, and meningioma." (PMID 25046975, 2014). "Additionally, their expression was positively correlated with that of Ki-67, PCNA and MCM2, which was consistent with the predictions of CancerSEA, implying that RACGAP1 and KPNA2 could facilitate breast cancer progression." (PMID 36200070, 2022). "Moreover, according to an NCBI GEO database (accession number: GDS2250), the expression of MCM2 is significantly higher in basal-like breast cancer than in normal breast cells and non-basal-like breast cancer cells." (PMID 26430873, 2015). "Thus, therapies targeting MCM2-targeting may be effective against TNBC cells and CSC-like breast cancer cells." (PMID 26430873, 2015). "Among the 147 prognostic gene pairs found in breast cancer, only a single gene pair IGKV1-5_MCM2 contains a meta-PCNA gene (MCM2) and no other prognostic gene pairs contain a meta-PCNA gene." (PMID 31856825, 2019).
cervical carcinoma (33 papers, 2012 to 2026). A carcinoma arising from either the exocervical squamous epithelium or the endocervical glandular epithelium. "Due to its ubiquitous nature, MCM2 is less likely to be considered on its own as a sensitive diagnostic marker for cervical cancer but shows a certain degree of promise as a concatenated detection method along with HPV typing, p16 or Ki-67 biomarkers." (PMID 31653153, 2019). "Consistent with this notion that upregulated expression of MCM2 is involved in the radio‐resistant cervical cancer cell, indicating that MCM2 is one potential regulatory factor in increasing radio‐sensitivity in cancer treatment." (PMID 36776764, 2023). "In cervical cancer tissue (K14E7E2 panel), the PCNA and MCM2 stainings exhibited a nuclear pattern and were uniformly distributed throughout the thickness of the epithelium, consistent with previous reports on cervical cancer." (PMID 37626777, 2023). "Previous studies have shown that miR‐186‐3p is downregulated in cervical cancer tissues and cell lines and that the expression of this miRNA directly controls MCM2 expression." (PMID 37517032, 2023). "Inhibiting MCM2 through miRNA and siRNA suppressed the proliferation of tumor cells in vitro in cancers including cervical cancer, MB, GBM, HCC, colon cancer and lung cancer." (PMID 36303105, 2022). "The mRNA expression levels of MCM2/3/4/5/6/7/8/9/10 in cervical cancer tissues and normal tissues were compared using the ONCOMINE database, and MCM2/3/4/5/6/7/8/10 expression was significantly increased in tumor tissues." (PMID 34404366, 2021). "MCM2 has been recognized as a useful marker in screening for cervical carcinoma oral squamous cell carcinoma and medulloblastoma." (PMID 33616161, 2021). "These genes and MCM2/3/4/5/6/7/8 were significantly related to the survival and prognosis of cervical cancer patients." (PMID 34404366, 2021). "MCM2 has been recognised as a useful marker in screening for cervical carcinoma oral squamous cell carcinoma and medulloblastoma." (PMID 31653153, 2019). "High MCM2 expression has been correlated with high-risk HPV and p16/CDKN2A expression in cervical cancer samples." (PMID 31653153, 2019). "MCM2, 4, 5,6 and 7 were also found to be upregulated in cervical cancer using semi-quantitative RT-PCR technique." (PMID 31653153, 2019). "Further assessment of MCM2 protein was performed to investigate it’s potential as a marker in detecting pre-cancerous lesions and cervical cancer." (PMID 31653153, 2019). "The combination of TOP2A and MCM2 in the commercial assay ProExCTM is used for immunohistochemistry analysis in cervical cancer samples." (PMID 27175798, 2016). "MCM2 and TOP2A, which have been widely reported as associated with cervical cancer, ranked 15th and 18th on the list, respectively." (PMID 23405241, 2013). "Targeting the KIF23/MYH9/MCM2/PCNA axis sensitises cervical cancer cells to cisplatin." (PMID 41940421, 2026). "In cervical cancer, MCM2 and MCM6 are upregulated while MCM4 is downregulated." (PMID 36765810, 2023). "However, the higher expression of MCM2, MCM4, and MCM6 is significantly associated with favorable overall survival in cervical cancer patients." (PMID 36765810, 2023). "Notably, the TOP2A/MCM2 combination was reported to be the best biomarker for discriminating between low- and high-grade squamous intraepithelial lesions for cervical cancer." (PMID 35884419, 2022). "In cervical cancer, miR-186-3p blocks tumorigenesis via suppressing MCM2." (PMID 34193018, 2021). "MCM2/3/4/5/6/7/8 might be used as potential indicators for survival in patients with cervical cancer, which needs more research and verification." (PMID 34404366, 2021). "These genes and MCM2/3/4/5/6/7/8 might have potential clinical value for the survival and prognosis of cervical cancer patients." (PMID 34404366, 2021). "The hub genes and MCM2/3/4/5/6/7/8 might have potential clinical value for the survival and prognosis of cervical cancer patients." (PMID 34404366, 2021).
cervical carcinoma (continued). "Several histological studies have reported the application of most common cellular biomarkers, including Ki-67, cyclin-dependent kinase inhibitor (p16), and ProEx C [topoisomerase II-alpha (TOP2A) and minichromosomal maintenance-2 (MCM2)] in the early diagnosis of cervical cancer." (PMID 34705880, 2021). "MCM10 and MCM2 overexpression have been reported in urothelial and cervical cancers." (PMID 30042885, 2018). "Previous studies have revealed the overexpression of mcm2 in cervical cancer by DNA microarray and transcriptional profiling, showing that mcm2 can be detected in various dysplastic and malignant processes, including cervical neoplasia related to high-risk HPV." (PMID 29137390, 2017). "Thus, MCM2 was introduced to improve the efficiency of cervical cancer screening." (PMID 36303105, 2022). "MCM2 protein strongly expressed in high-grade squamous intraepithelial lesion may be useful as a cascade screening tool for detecting precancerous changes in cervical cancer." (PMID 32964028, 2020). "This module's four proteins, MCM2, MCM10, POLA1, and TONSL, are cervical cancer driver genes based on the DriverDBv3 report." (PMID 37746664, 2023). "The logFC values of the MCM2, MCM10, POLA1, and TONSL in cervical cancer versus normal groups are 2.3, 3.37, 1.76, and 0.587, respectively." (PMID 37746664, 2023). "MCM2 and MCM4 suppress CRC and HPV‐type of cervical cancer progression, respectively." (PMID 38988047, 2024). "Moreover, we evaluated the expression of cell cycle-related genes (CCNA2, MCM2 and SKP2) in cervical cancer cells transfected with siNC or siACTL6A." (PMID 34395295, 2021). "We analyzed the expression of five cellular markers and their relation to SIL and cervical cancer development, and found that TOP2A/MCM2 staining is the best biomarker for discriminating between cervical lesion types, followed by p16INK4a, cyclin-E, Ki-67, and telomerase." (PMID 33413211, 2021). "Several studies showed increased MCM2 protein expression in HPV-infected cells and cervical cancer." (PMID 31653153, 2019). "With this analysis, only MCM4 of the MCM2-7 family was observed in early and late stage cervical cancer and not detectable in healthy epithelium and stroma cells." (PMID 29719595, 2018). "Interestingly, levels of members of the Minichromosome Maintenance (MCM) family (MCM2, MCM3, MCM4, MCM5, MCM6, MCM7) were found to be highly significantly increased in cervical cancer tissue from early and late stage patients as compared to healthy tissue." (PMID 29719595, 2018). "MCM2, 4, 5, 6, 7, 10 and RECQL4 are significantly over-expressed in cervical cancer." (PMID 23874974, 2013). "MCM2 which is over-expressed in cervical cancer irrespective of any clinical parameter is located at 3q21." (PMID 23874974, 2013). "Additionally, genomic studies, including mRNA analysis, demonstrated higher MCM2 levels in four cervical cancer cell lines compared to a normal cervical epithelial cell line." (PMID 40507244, 2025). "Capitalizing upon and targeting Minichromosome maintenance protein complex - specifically the MCM2, MCM4 and MCM6 subunits, ZWINT and CDC7 for experimental validation, may provide valuable insights in understanding and detection of progressing cervical neoplasia to cervical cancer at an early stage." (PMID 30150654, 2018). "MCM4, 5 and 6 also show differential expression in different types of lesion, while MCM2 and MCM10 are over expressed in cervical cancer irrespective of clinico-pathological parameters." (PMID 23874974, 2013). "Thus we aimed to evaluate the immunohistochemical expression of MCM-2 in abnormal cervical epithelium in women with and without HIV-1 co-infection to determine if MCM-2 is a valid prognostic biomarker for cervical cancer." (PMID 22493662, 2012).
ovarian carcinoma (22 papers, 2007 to 2024). A malignant neoplasm originating from the surface ovarian epithelium. "High expression of MCM2 level in malignant tumors, including ovarian cancer, is associated with several clinicopathological parameters such as advanced tumor grade, advanced stage, and poor prognosis." (PMID 31708970, 2019). "High expression MCM2 level in malignant tumors, including ovarian cancer, is associated with several clinico-pathological parameters such as advanced tumor grade, advanced stage, and poor prognosis." (PMID 29963273, 2018). "MCM2 is a DNA replication licensing factor that has been described as associated with worse outcome in ovarian carcinoma." (PMID 28968952, 2017). "High expression of cytoplasmic MCM2 exhibited a higher level of DNA damage-induced apoptosis in ovarian cancer cells and demonstrated excellent prognosis in patients with ovarian clear cell carcinoma." (PMID 36303105, 2022). "The MCM2 staining results demonstrated that many of the ovarian carcinoma cells were positive for MCM2." (PMID 29963273, 2018). "Regarding the expression of MCM2 protein in ovarian cancers, the immunohistochemical expression in ovarian high-grade serous carcinomas was higher than that in endometrioid carcinomas." (PMID 29963273, 2018). "Here, we demonstrated the cytoplasmic expression of MCM2 in a subset of ovarian cancer patients with clear cell carcinoma." (PMID 29963273, 2018). "In vitro experiments using ovarian cancer cells with cytoplasmic expression of MCM2 demonstrated that transfection of MCM2-ΔN enhanced DNA damage-induced apoptosis." (PMID 29963273, 2018). "MCM2 knockdown diminished viability and increased G0/G1 arrest in ovarian cancer cells." (PMID 37529110, 2023). "The inhibition of MUS81 expression by shRNA in human ovarian cancer cells (A2870 and SKOV3) induced a mild sensitization to olaparib (IC50: 4 vs. 7 μM for A2870, 6 vs. 9 μM for SKOV3) that was associated with an increase in the expression of MCM2." (PMID 36765954, 2023). "For example, MCM2 was highly expressed in tissue samples of lung cancer and ovarian cancer." (PMID 35693940, 2022). "In the present study, we analyzed the expression of MCM2 in human ovarian cancer." (PMID 29963273, 2018). "However, MCM2 localized to the nuclei in other types of ovarian carcinomas such as serous carcinoma and endometrioid carcinoma." (PMID 29963273, 2018). "In this study, there was not significant correlation between the labelling indices of MCM2 and Ki-67, suggesting that MCM2 may contribute to human ovarian cancer with a function different from proliferation." (PMID 29963273, 2018). "TMPyP4 at concentrations of 3, 6, 15, 30 or 60 μM significantly inhibited the proliferation and motility of human ovarian carcinoma A2780 cells but suppressed the expression levels of minichromosome maintenance protein-2 (MCM2) and carbonic anhydrase IX (CA-IX)." (PMID 28673331, 2017). "Furthermore, we introduced MCM2-ΔN, which lacks the nuclear localization signal (NLS) domain, into human ovarian cancer cells and investigated whether cytoplasmic localization of the MCM2 protein had apoptosis-enhancing effects in human ovarian cancer." (PMID 29963273, 2018).
ovarian carcinoma (continued). "In addition, the study indicated that TMPyP4-PDT may exhibit its antitumor activity by downregulating the expression of MCM2 and CA-IX in human ovarian carcinoma cells." (PMID 24959286, 2014). "Analyses of eight unique datasets were performed for MCM2, MCM4, and MCM6 in ovarian cancer, and three were significant." (PMID 34178669, 2021). "For example, MCM2 got a high level in HCC, oral squamous cell carcinoma, gastric cancer, breast cancer, colon cancer, and ovarian cancer." (PMID 32964028, 2020). "Univariate and multivariate analyses of the correlation of CDCA5, FOXM1, KIF15, MCM2, and ZWINT expression with overall survival (OS) among epithelial ovarian cancer patients." (PMID 31708970, 2019). "To validate the GSEA results, we then detected the expression of cell cycle (PCNA and PLK1), DNA replication (MCM2 and MCM3) and BER pathways-related proteins (PARP1 and PARP2) in ovarian cancer cells transiently overexpressed ARHGAP10." (PMID 27010858, 2016). "Microarray analysis revealed that the transcriptional expression of MCM2 in the cisplatin-resistant ovarian carcinoma cell was twice that of the non-drug-resistant group 55." (PMID 35173548, 2022). "MCM2, a highly conserved minichromosome maintenance protein (MCM), is involved in the initiation of eukaryotic genome replication and is closely related to the prognosis of ovarian cancer patients and the sensitivity to chemotherapy." (PMID 33952272, 2021). "Our results showed that miR-367 inhibited the expression of MCM2, MMP2, MMP9, and VEGF, suggesting that miR-367 may repress tumor cell proliferation, migration, invasion, and angiogenesis in ovarian cancer." (PMID 33024414, 2020).